KLF4 (KLF transcription factor 4)
Diseases named in the same sentence as KLF4 in open-access papers (continued):
Sharing a sentence is not in itself a finding about the gene and the disease.
tumor (continued). "The TWIST1-JAGGED1-NOTCH-KLF4 axis induces stem cell-like features and metastasis, where KLF4 and BMI1 contribute to TWIST1-induced tumor-initiating capacity, and knockdown of BMI1 expression leads to a reduction in the size and number of tumor spheroids." (PMID 37598158, 2023). "Other studies suggest that KLF4 inhibited the expression of phosphorylated JNK, ERK, and p38, which blocked the MAPK pathway signaling and thus inhibited the proliferation of tumor cells." (PMID 36761967, 2023). "Next, we discuss the contribution KLF4 has made towards the development, prognosis, and treatment of CRC, which will highlight KLF4′s role as both a tumor suppressor and oncogene." (PMID 37173904, 2023). "Although KLF4 inhibits the tumor proliferation and metastasis in most cases of SCLC and NSCL, KLF4 expression is higher in some NSCL than in normal tissue, which implies a positive association between KLF4 and NSCL." (PMID 37031197, 2023). "When tumor tissues were analyzed, the level of ufmylated RPL10 was markedly decreased from UFL1 knockdown, along with the decline of KLF4." (PMID 37280198, 2023). "These proteins have also been shown to modulate the pioneer factors KLF4, SOX2 and OCT4 in the context of tumourigenesis.KLF4 is dysregulated in many different types of cancer and can act here via tumor suppressing or oncogenic function." (PMID 37876935, 2023). "Here, we found that BMI1, CD44, SOX2, OCT4, UBE2C, CXCR4 CSCs marker genes are significantly upregulated, while IGF1-R, KLF4, ALDH1A1, CD133, FAM3C are downregulated in the tumor core vs healthy mucosa of 24 patients with OSCC." (PMID 38096163, 2023). "Increased levels of KLF4 and other stemness markers were observed in the CD133+ CRC stem cell population, which is responsive to the WNT/β-catenin pathway which promotes tumor growth and metastasis." (PMID 37173904, 2023). "The most five active regulators were identical in tumor and normal tissues, SPI1, CEBPB, JUNB, FOS, and KLF4." (PMID 37335089, 2023). "Overexpressing KLF4 resulted in a decrease in PITX1 and Ki67 expression levels, and an increase in FLG2 staining intensity, inhibiting tumor growth." (PMID 37841446, 2023). "Compared to para-tumor specimens, the mRNA levels of KLF5, KLF7, KLF8, and KLF13 were elevated, whereas those of KLF4, KLF6, and KLF10 were reduced in HCC specimens." (PMID 37554278, 2023). "In cell lines, KLF4 expression inversely correlated with DYRK2 expression and induced tumor formation in a xenograft mouse model." (PMID 37886981, 2023). "NANOG also works together with other stemness factors, such as KLF4, MYC, OCT4, or SOX2, to control target genes that have important functions in embryonic stem cells and, plausibly, in tumor cells." (PMID 37165076, 2023). "This XIST-driven production of IL-6 from ALDH− bulk tumor cells preferentially binds to IL6R on ALDH+ CSCs to drive STAT3 activation and expression of key CSC factors (i.e., c-MYC, KLF4 and SOX9), promoting self-renewal of ALDH+ CSCs." (PMID 36922677, 2023). "In the present study, intense nuclear immunostaining for KLF4 was observed in AME, predominantly in the tall columnar cells located on the periphery of the tumour island." (PMID 37559082, 2023). "The sustained expression of KLF4 promotes the growth of hypo-perfused hypervascularity by regulating NOTCH, thus leading to reduced tumor growth." (PMID 36761967, 2023). "KLF4 is a member of the KLF-like factor subfamily of zinc finger proteins, which play an ambivalent role in tumorigenesis as either a tumour suppressor or an oncogene in a number of cancers." (PMID 36539799, 2022). "As a proof-of-principle, we treated APKS mouse tumor organoids with KLF4 agonist APTO-253, and it significantly suppressed tumor organoid growth." (PMID 36276637, 2022). "KLF4, on the other hand, is demonstrated to decrease the proliferation of CRC cells and can play a tumor suppressor role in this malignancy, according to a study." (PMID 36344988, 2022).
tumor (continued). "Overexpression of microRNA-92a (miR-92a)promotes tumour growth and invasion in CRC by targeting KLF4 and downstream p21, whereas downregulation of miR-92a can result in the apoptosis of CRC cells." (PMID 36776356, 2022). "In vitro and in vivo studies demonstrated that circPLEKHM3 played an anti-tumor role by sponging miR-9 to enhance the tumor-suppressive effect of BRCA1, DNAJB6, and KLF4, and consequently inactivated the AKT signaling in EOC." (PMID 36428803, 2022). "Our results support previous findings that KLF4 levels and activity were increased in HPV-positive cells in vitro and in HNSCC tumor tissue samples." (PMID 35219646, 2022). "To further analyze the effect of deguelin on tumor size and expressions of PTEN and KLF4, we inoculated PC9 cells subcutaneously into BABL/c mice and injected deguelin." (PMID 35637651, 2022). "Mice implanted with MDA-MB-231 NTC or A2BR knockdown subclones were treated with 10 mg/kg paclitaxel every 5 days for three doses and tumor samples were collected for ChIP followed by qPCR with primers flanking FOXO3 binding site of NANOG, SOX2 and KLF4 genes." (PMID 35401817, 2022). "Up-regulation of ten DEGs in PAAD tumor is in concordance with the up-regulation of master regulators CTCF, IRF1, and KLF4, while POLR2A and STAG1 remain unchanged." (PMID 35453789, 2022). "SOX2, KLF4, NANOG, and OCT4 are notorious for their specific expression in CSCs of HNSCC, which promoted stemness and tumor progression and lead to poor prognosis." (PMID 36451812, 2022). "The impact of PPARγ on cancers is complex and bidirectional, PPARγ acts as a tumor promoter by induction of lipogenic gene ACLY, MIG12, FASN, and NR1F1, stem cell-related gene KLF4, ALDH and upregulation Nox1 ROS, and VEGF." (PMID 36587194, 2022). "NANOG also works together with other stemness factors, such as MYC, OCT4, KLF4, SOX2, SOCS2, or ALDH1A1, to control a set of target genes that have important functions in embryonic stem cells and, plausibly, in tumor cells." (PMID 35104240, 2022). "We observed an additional tumour with integration in KLF14 located in 7q32.3, one in KLF4 located in 9q31.2, and one in KLF6 located in 10p15.1." (PMID 35398964, 2022). "Conversely, a recurrent mutation KLF4 p.K409Q has not been detected in our grade 2/3 samples, which supports that this variant might be predominantly harbored in low-grade tumors and possibly associated with a favorable prognosis without tumor recurrence." (PMID 35774130, 2022). "Tissue microarrays of tumor samples for patients between 2007 and 2016 were used for immunodetection of Nestin, SOX2, SOX9, KLF4, NANOG, CD133 cMYC, and Ki67." (PMID 35795469, 2022). "Finally, stable KLF4-overexpression might sensitize HNSCC tumor cells for Cisplatin treatment." (PMID 36289744, 2022). "There are multiple transcriptional factors, such as MYC, EZH2, TRIM24, KLF4, and BRD4, that can regulate AR transcription by binding to its promoter in tumor cells." (PMID 34323404, 2021). "As we mentioned, miR-2909 is capable of regulating the expression of KLF4, which in pediatric ALL functions as a tumor suppressor, regulates cell cycle and apoptosis." (PMID 33412518, 2021). "BMI1 and KLF4 were revealed to be direct targets of miR-135a, and miR-135a had a similar effect as the combination of si-BMI1 and si-KLF4 on inhibiting tumor progression and the expression of BMI1 and KLF4 in vivo." (PMID 33828977, 2021). "The results revealed that most of the SRGs were differentially expressed and most of them were found increased in tumor tissues except for KIT, NGFR, SOX2 and KLF4 (sFigure 2A)." (PMID 34587919, 2021). "In conclusion, this study revealed that abridged miR-135a expression in OS, while restoration of miR-135a suppressed tumor invasion and pulmonary metastasis by targeting BMI1 and KLF4 in vitro and in vivo." (PMID 33828977, 2021).
tumor (continued). "METTL14 performed tumor suppressor functions similar to that of METTL3 in the development of GSCs by targeting mRNA levels of ADAM19, EPHA3 and KLF4." (PMID 34521394, 2021). "Our present study showed that miR-92a-3p was increased in CC tissues when compared with non-tumor tissues, and even higher in DDP-resistant CC tissues, while an opposite result was observed in the expression of KLF4." (PMID 35095494, 2021). "In gastrointestinal tumors, changes in the expression levels of KLF4 and KLF5 have an impact on tumor development." (PMID 34367275, 2021). "UALCAN was adopted to analyze the changes in the methylation levels of KLF4 and KLF5 promoters between normal and tumor tissues of the gastrointestinal tract." (PMID 34367275, 2021). "In the intratubular infiltration areas, nests of cells expressing both OCT4/KLF4 and PTTG1 presence were consistent for a sub-population of tumor stem cells OCT4- and KLF4- positive." (PMID 34209730, 2021). "As to how HAT1 regulates AR expression, there are multiple transcriptional factors, such as MYC, EZH2, TRIM24, KLF4, and BRD4, regulate AR transcription by binding to its promoter in tumor cells." (PMID 34323404, 2021). "We have previously identified two CSC subpopulations within mHNcSCC: an OCT4+/SOX2+/NANOG+/KLF4+/c-MYC+ subpopulation within the tumor nests (TNs) and an OCT4+/SOX2+/NANOG-/KLF4+/c-MYC+ subpopulation within the peritumoral stroma (PTS)." (PMID 34621666, 2021). "KLF4 and KLF5 were differentially expressed in normal and tumor tissues of the gastrointestinal tract, and their differential expression is related to several genes or pathways." (PMID 34367275, 2021). "Using the EdU assay, we observed that si-KLF4 and PTC-209 significantly inhibited tumor cell proliferation compared with each control group (*p < 0.05; **p < 0.01)." (PMID 33828977, 2021). "In the next step, expression level of stemness relatedgenes (OCT4, SOX2, KLF4, c-MYC and NANOG) and EMTtranscription factors (CDH1, CDH2, SNAIL1, TWIST1,TWIST2 and ZEB1) were evaluated in all tumor samples andmammospheres." (PMID 31376329, 2020). "Further statistical analysis showed that KLF4 expression was positively correlated with the expression of CD9 (r = 0.510, P < 0.01) and CD81 (r = 0.382, P < 0.05) in tumor tissues." (PMID 32350244, 2020). "RT‐qPCR was then conducted to detect the mRNA expression of KLF4 and LINC00673 in tumours, and Western blot analysis was conducted to determine KLF4 protein expression." (PMID 31881124, 2020). "KLF4 directly activates the expression of the gene coding for tissue inhibitor of metalloproteinases 3 (TIMP3), which acts as a tumor suppressor." (PMID 33266506, 2020). "The m6A modification catalysed by METTL3 is recognized by YTHDF2 to mediate the mRNA decay of tumour suppressors SETD7 and KLF4, which consequently induces the BCa progression." (PMID 32126149, 2020). "De novo PITX1 expression in tumor-propagating cells controlled self-renewal and proliferation through co-binding with SOX2 and TRP63 and repressing KLF4, which maintains differentiation, in murine SCC." (PMID 33202305, 2020). "Altogether, a significantly decreased expression of MCT1 (p: 0.025) and a significantly increased expression of GFAP (p: 0.010), β-catenin (p: 0.039), KLF4 (p: 0.035) and OCT4 (p: 0.026) was detectable at the edge of the tumor compared with the center." (PMID 32872409, 2020). "Hypermethylation in gene promoters is a general epigenetic modification in cancer formation, especially for inhibition of tumor-suppressive genes such as PCDH10, DKK1, and KLF4." (PMID 32701143, 2020).
tumor (continued). "In agreement with previous reports, KLF4 mRNA expression was remarkably downregulated in tumor tissues, and lower expression of CD9 and CD81 mRNAs were observed in tumor tissues as compared with adjacent normal tissues." (PMID 32350244, 2020). "KLF4 activity as a transcriptional transactivator is negatively regulated by DEAD box RNA helicase 17 (DDX17), which displays a tumor promoting function in HCC." (PMID 33266506, 2020). "One population within the tumor niche had the markers SOX2+/NANOG+/KLF4+/c-MYC+/OCT4−, and two populations in the peritumoral stroma had the markers SOX2+/NANOG+/KLF4+/c-MYC+/OCT4− and SOX2+/NANOG+/KLF4+/c-MYC+/OCT4+." (PMID 32974184, 2020). "Signaling elicited by the stem cell factors SOX2, OCT4, KLF4, and MYC not only mediates reprogramming of differentiated cells to pluripotency but has also been correlated with tumor malignancy." (PMID 32427884, 2020). "Immunofluorescence staining performed on three of these mHNcSCC samples demonstrated expression of c-MYC on cells within the tumor nests (TNs) and the peri-tumoral stroma (PTS) that also expressed KLF4." (PMID 32850316, 2020). "We were therefore able to analyze the expression of NANOG, SOX2, OCT4, AGR2, KLF4, and NOTCH1 in only 11 tumor samples and corresponding TANT (22 FFPE tissue samples)." (PMID 32733958, 2020). "KLF4 also directly binds to the promoter of the gene coding for Ring1- and YY1-binding protein (RYBP), a tumor suppressor, and positively regulates its expression." (PMID 33266506, 2020). "Consistent with the role of SAM as a methyl donor, NCT-503 decreased DNA and histone methylation, and led to the re-expression of ID4, KLF4, CDKN2B and TXNIP tumor suppressors." (PMID 32138178, 2020). "One patient (St23784/17) had amplifications in the 3q, 6q, 8q, 9q, and 10q22.1 regions of stemness gene localization in her tumor (the following genes were amplified: SOX2, MYC, KLF4, NOTCH1, NODAL)." (PMID 32523653, 2020). "KLF4 has been characterized as a tumor-suppressor in EOC, as KLF4 downregulation correlated with accelerated EOC proliferation, invasion, and migration and poor patient survival." (PMID 32156068, 2020). "Studies have shown that miR-7-5p can inhibit tumor development by regulating the PI3K/Akt pathway and the expression of the target gene KLF4." (PMID 33490103, 2020). "We analyzed for the first time the relative mRNA expression for OCT4, SOX2, KLF4, C-MYC, and NANOG in tumor and normal cells." (PMID 31885625, 2019). "Tumor spheres derived from OSCC cells are CSC-enriched cell population as stemness transcription factors, NANOG, OCT4, KLF4, LIN28, and SOX2 were enriched in tumor spheres." (PMID 31040921, 2019). "That is, either of the two mechanisms will lead to release more sponged miR-9 into tumor tissues, which subsequently reduces the endogenous suppressive effect of BRCA1, DNAJB6 and KLF4." (PMID 31623606, 2019). "Next, we performed a qRT-PCR analysis on treated and untreated tumor cells revealing significant downregulating of NCAM1 expression, as well as downregulation of several self-renewal genes (e.g., LIN28A, OCT4, and KLF4) in the anti-NCAM1 treated cells." (PMID 31477684, 2019). "Hence, we assumed that KLF4 may affect the tumor metastasis and distant invasion." (PMID 31969824, 2019). "KLF4 and BRCA1 exhibited stronger staining in tumor tissues of immunodeficient mice injected with A2780 scramble cells than the mice injected with A2780 sh-circPLEKHM3 cells." (PMID 31623606, 2019). "si-hVDAC1 tumor treatment markedly decreased the expression of CSCs markers, such as CD133, SOX2, KLF4, Nestin, and CD44, as evaluated by quantitative immunoblotting and qRT-PCR." (PMID 31661894, 2019). "Statistical analysis revealed that the expression of SIRT4 was positively correlated with the expression of KLF4 in the two cohorts, and both SIRT4 and KLF4 expression were decreased in tumor tissues." (PMID 30952833, 2019).
tumor (continued). "Results showed that ZBTB28 inhibited NANOG, BMI1, OCT4, KLF4, TIP30 and STAT3 mRNA expression in tumor cells." (PMID 31754389, 2019). "To determine the correlation between KLF4 expression and EMT in CRC, we performed immunofluorescence analysis of matched pairs of archived samples from patients after tumor resections." (PMID 32566755, 2019). "In contrast, in the tumor samples from the same patient [SB396T], the expression of KLF4 is downregulated in the epithelial cells, which is accompanied by a significant increase in the expression of TWIST." (PMID 32566755, 2019). "In contrast, NCOA2, VEGFA, ACPP, KLF4, and TMPRSS2 had significantly higher tumor vs. normal ratio in BCR cases." (PMID 31741711, 2019). "Future studies will involve assessing KLF4 protein expression in mice tumors as well as the expression of HDAC2, HDAC3 and hTERT in the tumor tissues." (PMID 29899271, 2018). "In the case of MDA-MB-231-derived tumours treated with si-hVDAC1, the expression of ALD1HA1, KLF4, SOX2, CD133 and EPCAM were highly reduced, again as analysed by IHC, immunoblotting or q-RT-PCR." (PMID 30544833, 2018). "Both KLF4 and KLF5 interact with the same cis-element, inhibit each other’s activity, and they also exhibit tumor suppressor and oncogenic activities, respectively." (PMID 29914355, 2018). "Regarding the role of self-renewal factors such as SOX2, NANOG, KLF4, and SALL4 in biology of tumor cells we assessed the probable role of KCTD12 in regulation of such factors in the levels of mRNA expression." (PMID 30157793, 2018). "Apart from this, the expression level of CSCs‐related proteins:CD44, ALDH1, KLF4, SOX2 and EMT‐related proteins: Slug, Vimentin were also remarkably elevated in mice SCCHN tumour than that in wild‐type normal tongue tissue." (PMID 29193723, 2018). "KLF4, a related member of the KLF family of transcription factors, has been previously identified as a tumor suppressor in B-cell lymphoproliferative disorders." (PMID 30038712, 2018). "TIC or CSC is a stem cell that facilitates tumor initiation, however, re-expression of DACH1 decreased the tumor and mammosphere formation, reduced the CD44high/CD24low proportion in BTIC, and repressed the expression of Sox2, Oct4, Nanog, KLF4 and c-Myc." (PMID 30261897, 2018). "Here, we showed that VDAC1 silencing in A549 cell-derived tumours resulted in reduced expression of lung-specific CSC markers, such as ALDH1, KLF4, SOX2, CD133, CD44, CD144, EPCAM, Oct3/4 and Nanog." (PMID 30544833, 2018). "In contrast, normal canine osteoblasts possessing high basal levels of miR-34a expressed significantly lower levels of KLF4 and SEMA3E compared to OSA tumor samples." (PMID 29293555, 2018). "Recent studies proved that some oncogenes and tumour suppressors, such as PTEN, HIF-1a, Myc, KLF4, FOXM1, and Gas1 regulate glycolysis in cancer cells." (PMID 29463261, 2018). "IF IHC staining showed the presence of a SOX2+/NANOG+/KLF4+/c-Myc+/OCT− CSC subpopulation within the tumor nests, and a SOX2+/NANOG+/KLF4+/c-Myc+/OCT4− CSC subpopulation and a SOX2+/NANOG+/KLF4+/c-Myc+/OCT4+ CSC subpopulation within the peritumoral stroma." (PMID 29404335, 2017). "KLF4 and OCT4 had a very low expression in all the tumor components with respect to the kidney; in contrast, there were expression differences between components for the other three markers." (PMID 29383160, 2017). "VDAC1-based peptide tumor treatment eliminated GSCs, as reflected in the marked decrease in the expression levels of all tested stem cell markers, namely Sox2, Nestin, CD133, Klf4, S100B and NGFR." (PMID 28412744, 2017). "To further evaluate the expression and subcellular localization of KLF4 in UBC tissue and adjacent non-tumor tissue, we analyzed the immunohistochemistry (IHC) results which showed KLF4 was located in cytoplasm." (PMID 29254226, 2017).